ABCB1 (ATP binding cassette subfamily B member 1)
Diseases named in the same sentence as ABCB1 in open-access papers (continued):
Sharing a sentence is not in itself a finding about the gene and the disease.
lymphoma (32 papers, 1989 to 2025). A malignant (clonal) proliferation of B- lymphocytes or T- lymphocytes which involves the lymph nodes, bone marrow and/or extranodal sites. "In canine lymphoma, mutations in the ABCB1 gene may not only increase drug efflux but also impact the expression and conformation of intracellular drug targets, contributing to reduced sensitivity to chemotherapeutics like vincristine and doxorubicin." (PMID 40872698, 2025). "In dogs, overexpression of ABCB1 has been documented in certain lymphomas and osteosarcomas, contributing to resistance against drugs like doxorubicin and vincristine." (PMID 40872698, 2025). "The MDR reversal potential of compounds 1–25 was assessed, by functional and chemosensitivity assays, using resistant human ABCB1-gene transfected L5178Y mouse lymphoma cells as a model." (PMID 38665830, 2024). "These compounds were assessed for their cytotoxic effect and ABCB1 modulating properties against parental and ABCB1 overexpressing mouse T lymphoma cells." (PMID 36747956, 2023). "Among them compound 53 displayed the highest inhibition of Rh123 efflux of human ABCB1 gene transfected mouse lymphoma cells (FAR = 102.1 at 40 μg/ml)." (PMID 35418870, 2022). "Their biological activity against MDR was evaluated through a drug combination assay in the L5178Y mouse T lymphoma cell line transfected with the human ABCB1 gene." (PMID 35418870, 2022). "Their efficacy was 2–3 times higher than that of the positive control verapamil in a mouse T-lymphoma ABCB1-transfected cell model (FAR = 12.5 at 20 μM)." (PMID 35418870, 2022). "Their biological activity was investigated against MDR in human ABCB1-gene transfected mouse lymphoma cells." (PMID 35418870, 2022). "P-gp inhibitory activity of compounds 1 and 3–21 on human ABCB1-transfected L5178Y mouse lymphoma cells." (PMID 34577562, 2021). "Compounds 3–32 were evaluated as multidrug resistance (MDR) reversers through functional and chemosensitivity assays in a human ABCB1-transfected mouse T-lymphoma cell model, overexpressing P-glycoprotein." (PMID 34577562, 2021). "Their ability to inhibit P-gp drug efflux activity was assessed, by flow cytometry, in human ABCB1-gene transfected mouse T-lymphoma cells." (PMID 34577562, 2021). "For this, we determined the ABCB1 inhibiting properties of our compounds in a mouse T-lymphoma cell line model and then evaluated the drug-enhancing properties of selected compounds in a co-application with clofazimine in our Mtb strain." (PMID 31398786, 2019). "A checkerboard microplate method was applied to study the drug interactions of Se-compounds and clinically relevant chemotherapeutic drugs against the multidrug-resistant (MDR) subtype of mouse t-lymphoma cells overexpressing the ABCB1 transporter." (PMID 30669343, 2019). "It has generally been thought that lymphomas in humans and dogs acquire multidrug resistance from the continuous activation of drug transporters, such as ABCB1 and ABCG2, after long-term exposure to anticancer drugs, inducing chemical tolerance in the patient." (PMID 28489881, 2017). "ABCB1 in turn represents a gene where exon 2 skipping occurring in the promoter region is an unfavorable event correlating with lymphoma progression." (PMID 28841210, 2017). "In terms of lymphoma, a study examined the methylation status of the ABCB1 gene in patients with hematopoietic malignancies, including five NHL patients, but the detailed methylation status of the gene in those NHL patients was not described." (PMID 29061940, 2015). "We previously showed the high expression level of the ABCB1 gene in a proportion of dogs with lymphoma that developed multidrug resistance." (PMID 29061940, 2015). "Six new jatrophane-type diterpenoids and three known diterpenes were isolated from the whole undried plants of Euphorbia esula, most of which were able to enhance the Rhodamine 123 (Rh123) accumulation in human ABCB1-transfected L5178Y mouse T-lymphoma cells, overexpressing ABCB1." (PMID 35418870, 2022).
lymphoma (continued). "P-gp inhibitory activity of compounds 22–32 on human ABCB1-transfected L5178Y mouse lymphoma cells." (PMID 34577562, 2021). "It has been demonstrated that a selenoanhydride derivative and some selenoester derivatives have potent anticancer activity against ABCB1 expressing in MDR mouse T-lymphoma cells and MDR colon adenocarcinoma cells due to ABCB1 inhibition and apoptosis induction." (PMID 34572790, 2021). "Our previous studies have demonstrated that the selenoanhydride 1 and selected selenoesters 2–11 have shown potent anticancer activity against ATP-Binding cassette sub-family B member 1 (ABCB1)-overexpressing MDR mouse T-lymphoma cells and MDR colon adenocarcinoma cells." (PMID 31014009, 2019). "However, the associations of the mutations of the ABCB1 or ABCG2 gene with drug resistance are unclear in human and canine lymphomas." (PMID 29061940, 2015). "The phenylselenoethers exhibited P-glycoprotein (ABCB1) MDR efflux pump inhibitory activity and possessed interesting cytotoxic and antiproliferative MDR mouse T-Lymphoma cells reaching, with compound 11, the submicromolar range." (PMID 36678733, 2022). "Exogenous application of TGFβ induces spontaneous neoplastic transformation of hepatocytes, correlating with augmented ABCB1, as well as increasing the side population, ABCB1 mRNA, TGFβ receptor mRNA, and MAPK signaling in lymphoma cell lines." (PMID 35582031, 2021). "In order to determine MDR efflux pump modulatory properties for the new compounds, a dye-substrate accumulation assay was performed in two T-lymphoma cell lines, i.e., parental (PAR) and multidrug resistant one (MDR) with overexpression of ABCB1." (PMID 32403277, 2020). "ABCB1, also called MDR1, is the prototype of ATP-binding cassette transporters and is overexpressed in up to 80% of relapsed lymphomas." (PMID 27835906, 2016). "Our previous studies also revealed that the JNK pathway downregulated ABCB1 gene expression and the MAPK/ERK and JNK pathways downregulated ABCG2 gene expression in those lymphoma cell lines." (PMID 29061940, 2015). "We revealed that this drug also had antitumor effects in canine lymphoid tumor cells and decreased ABCB1 gene expression through activation of the JNK pathway, leading to a reduction of IC50 values for vincristine in a canine lymphoma cell line." (PMID 29061940, 2015). "Also, it has been showed that TGF-β signaling conducted the increased gene expression of drug efflux pumps ABCB1 and LRP in the side populations of canine lymphoma cell lines." (PMID 33961622, 2021). "In veterinary medicine, we revealed the upregulation of ABCB1 and LRP gene expression through the activation of the MAPK/ERK pathway by examining the side population, which is thought to contain the cancer stem cell fraction, in canine lymphoma cell lines." (PMID 29061940, 2015).
neutropenia (27 papers, 2014 to 2025). A decrease in the number of neutrophils found in the blood. "An association of ABCB1 with the incidence of anthracyclines toxicity was reported previously, especially neutropenia." (PMID 40283974, 2025). "They found that carriers of the homozygous common type (GG) of ABCB1 (rs1045642) were at higher risk of developing severe amrubicin-induced neutropenia." (PMID 40283974, 2025). "The results of our study showed a significant increased risk of recurrent severe and early neutropenia in carriers of the ABCB1 rs17064 genotype AT." (PMID 39596349, 2024). "Recently, the association between ABCB1-rs1128503 genotype and palbociclib-related neutropenia risk was also confirmed by the pharmacogenetic analyses in PALOMA-2 and -3." (PMID 35942220, 2022). "On the other hand, in a Caucasian cohort, the variant alleles of ABCB1 3435C>T, 2677G>A/T and 1236C>T and their haplotypes were associated with higher organ toxicities (renal, hepatic and neutropenia), as well as with higher induction death." (PMID 35456712, 2022). "In contrast, the ABCB1 c.3435C>T and c.2677G>T/A polymorphisms (dominant model) were associated with more pronounced neutropenia in another study." (PMID 33326171, 2021). "The T alleles of ABCB1 rs1128503 and ABCB1 rs2032582 were reported to be correlated with decreases in the risk of neutropenia and diarrhea, respectively." (PMID 33762959, 2021). "Dogs harbouring the ABCB1‐1Δ mutation in the MDR1 gene also have been shown to be at greater risk for experiencing neutropenia following vincristine treatment." (PMID 33369129, 2021). "In particular, in a study of paclitaxel-treated patients with ovarian cancer, carriers of ABCB1 3435T or 1236T experienced a severe neutropenia as compared with carriers of the C allele (p=0.03 and p=0.06 respectively)." (PMID 29861877, 2018). "The association between severe neutropenia and ABCB1 3435T SNP has been subsequently confirmed in several studies of breast and prostate cancer patients treated with docetaxel." (PMID 29861877, 2018). "ABCB1-3435C>T was found to be associated with increased risk of neutropenia in Lebanese pediatric ALL patients and with anemia and thrombocytopenia in a Danish population." (PMID 27618021, 2016). "In their study, Sissung and colleagues described an association between ABCB1 gene polymorphisms and toxicities such as nephropathy, neutropenia, and survival in 23 patients who were undergoing chemotherapy." (PMID 28036387, 2016). "The ABCB1 2677T allele was associated with reduced neutropenia risk and inferior radiological response and the ABCB1 1236 T allele was associated with reduced risk of neutropenia and diarrhea." (PMID 26244574, 2015). "Likewise, previous research aimed to assess the use of ABCB1 polymorphism as a predictor of neutropenia with amrubicin, which is one of the anthracyclines." (PMID 40283974, 2025). "In our study, the risk of severe recurrent neutropenia (grades 3 and 4) was independently influenced by the ABCB1 rs17064 genotype AT (OR 5.13; 1.38–19.02; p = 0.014), UGT2B4 rs1131878 genotype AG (OR 3.78; 1.26–11.24; p = 0.016), and ALDH5A1 genotype AC (OR 3.94; 1.34–11.53; p = 0.012)." (PMID 39596349, 2024). "There is a strong association of the FLT3 738T genotype with leucopenia; FLT3 738T, ABCB1 1236T, ABCB1 3435T, ABCB1 2677T, ABCG2 421A alleles and the ABCB1-3435-1236-2677 TTT haplotype with neutropenia; and primary resistance and inferior survival with the ABCB1-3435-1236-2677 TTT haplotype." (PMID 34948113, 2021).
neutropenia (continued). "Pharmacogenomic profiles can show a predisposition to a higher neutropenia and neuropathy risk by reveling higher transmembrane expression of the ABCB1 (3435TT and 2677TT/AA), variant phenotype, conferring the excessive extrusion of taxane from neoplastic cells and causing high plasma concentration." (PMID 29163177, 2017). "For example, a study focusing on the C3435T variation of the ABCB1 gene in breast cancer patients revealed that individuals with the TT genotype experienced higher area under the curve (AUC) values and OS rates, albeit with an elevated risk of diarrhea and neutropenia." (PMID 39598531, 2024). "In patients receiving docetaxel and doxorubicin, those with the ABCB1-3435 TT genotype were more prone to develop grade 3 or higher neutropenia (p = 0.039) and diarrhea." (PMID 39598531, 2024). "Multivariate analysis showed a significant protective effect of ABCB1-rs1128503 CC wild-type genotype in terms of neutropenia." (PMID 35942220, 2022). "Several novel findings were reported with the combinations of ABCB1 and SLC polymorphisms, including higher hepatic and renal toxicities, mucositis and neutropenia, as well as a higher incidence of induction death." (PMID 35456712, 2022). "Key takeaway: The pharmacological evaluation highlighted the presence of three risk factors for the development of neutropenia: 1) overexposure to 125 mg/day palbociclib; 2) baseline ANC median value below 3.60 (×103/mm3); 3) low function ABCB1 haplotype." (PMID 35942220, 2022). "In one study, the ABCB1 genotype predicted not only neutropenia, but also anemia (p=0.044 and p=0.029 respectively)." (PMID 29861877, 2018). "We observed significant associations of FLT3 738T (OR=2.7), ABCB1 1236T (OR=0.3), ABCB1 3435T (OR=0.1), ABCB1 2677T (OR=0.4), ABCG2 421A (OR=0.3) alleles and ABCB1 3435, 1236, 2677 TTT haplotype (OR=0.1) on neutropenia." (PMID 26244574, 2015). "Since variants of not only UGT1A1, but also other genes, including UGT1A7, UGT1A9, ABCB1 and ABCC2, have been reported to be involved in the occurrence of CPT-11-induced severe neutropenia, rare variants of these genes should be investigated in the future." (PMID 24932285, 2014). "The results indicated that ABCB1 SNP might be a good predictor of worse AC regimen-induced neutropenia." (PMID 40283974, 2025). "During the AC chemotherapy cycles, patients carrying the GG genotype of the ABCB1 gene exhibited a significant increase in neutropenia grade after the second and fourth cycles, while lymphocytopenia grade significantly increased after the third and fourth cycles compared to baseline (p < 0.05)." (PMID 40283974, 2025). "The ABCB1 rs17064 heterozygous variant (AT) (OR 4.56; 1.25–16.63; p = 0.021), DPYD rs291583 allele G (OR 1.83; 1.03–3.21; p = 0.036) and positive HER2 status (OR 1.69; 0.99–2.87; p = 0.049) increased overall neutropenia risk." (PMID 39596349, 2024). "Qualitative hematological toxicity variables, including thrombocytopenia, leukopenia, neutropenia, lymphocytopenia, and anemia, were assessed at five different time points for their correlation with various alleles of the CYP2C19, ALDH3A1, SLC22A16, and ABCB1 genes." (PMID 40283974, 2025). "Similarly, among patients with the GA+AA genotype of the ABCB1 gene, the neutropenia grade showed a significant increase following the second cycle, and the lymphocytopenia grade significantly increased after the fourth cycle compared to pre-treatment levels (p-value < 0.05)." (PMID 40283974, 2025). "ABCB1 rs2032582 (G2677TA, Ala893Ser) displayed differential genotypic distribution between groups with grade 4 neutropenia and grade 1-3 neutropenia in 107 NSCLC patients (p = 0.030)." (PMID 39234108, 2024).
cervical carcinoma (26 papers, 2014 to 2025). A carcinoma arising from either the exocervical squamous epithelium or the endocervical glandular epithelium. "In vincristine-resistant human cervical carcinoma (KB-vin) cells, characterized by high ABCB1 mRNA expression and minimal expression of ABCC1 and ABCG2, β-carotene (100 μM) significantly upregulated ABCB1 mRNA levels." (PMID 41303640, 2025). "Their results suggested that the activated GPR81, stimulated by L- and D-lactate, up-regulated the protein and mRNA expressions of the ATP-binding cassette subfamily B member 1 (ABCB1) to enhance the doxorubicin resistance in the cervical cancer cell." (PMID 36612084, 2022). "For example, the lactate receptor (HCAR1/GPR81) has been reported to be responsible for ABCB1 up-regulation in human cervical cancer cells to mediate doxorubicin resistance." (PMID 33593355, 2021). "Furthermore, HCAR1 was observed to be involved in lactate-stimulated expression of ATP-binding cassette sub-family B member 1 (ABCB1), a key mediator of chemoresistance, in cervical cancer cells." (PMID 40333742, 2025). "Similarly, MUC1 induced the resistance of both lung and cervical cancer cell lines to paclitaxel by upregulating ABCB1 in an EGFR-dependent manner." (PMID 38254882, 2024). "Moreover, studies have shown that ABCB1, commonly referred to as P-glycoprotein (P-gp), is responsible for the efflux of cisplatin from tumor cells, leading to drug resistance in cervical cancer." (PMID 38067428, 2023). "In our cervical cancer xenograft mouse model, co-administration of PTX with EGFR inhibitor erlotinib significantly prevented the tumor growth and relapse, which was associated with reduced expression of MUC1 and ABCB1, and diminished activity of EGFR." (PMID 28796259, 2017). "Therefore, we tested the cervix carcinoma cell line KB-3-1 and its ABCB1-overexpressing sublines KBC-1 and KB-V1 for sensitivity against vincristine and vinblastine in absence and presence of nintedanib." (PMID 27367030, 2016). "In contrast, ABCB1 expression remained unaffected by trans-chalcone in BT-20 and by CYB-2 and B20 in cervical cancer cells." (PMID 40362377, 2025). "Promoter methylation of ABCB1, ABCC1, and ABCG2 has been determined in the cervix cancer line KB-3-1 and two drug-resistant sublines, KBC-1, selected against colchicine and overexpressing ABCB1, and KB-1089, selected against the thiosemicarbazone KP1089 and overexpressing ABCC1 and ABCG2." (PMID 33066132, 2020). "Supporting the idea that MEOX2 and TWIST1 contribute to oncologic treatment resistance, functional studies have shown that shRNA-mediated TWIST1 silencing in cisplatinum-treated cervical cancer cells regulates the expression of the multi-drug resistance receptor, MDR1/P-gp, also known as ABCB1." (PMID 25460568, 2014).